HBZ (hemoglobin subunit zeta)
Description:
The zeta chain is an alpha-type chain of mammalian embryonic hemoglobin.
Synonyms: HBZ1; HBZ-T1; HBAZ
Tractability: Small molecule: a structure with a bound ligand is known. PROTAC: ubiquitination databases record sites on it.
Gene: Protein-coding gene on chromosome 16 (142,728 to 154,503, forward strand). Ensembl gene ENSG00000130656.
Subcellular location (Human Protein Atlas): Cytosol; Nucleoplasm
Gene Ontology:
Molecular function: protein binding; heme binding; oxygen carrier activity; iron ion binding; oxygen binding
Biological process: oxygen transport; carbon dioxide transport; erythrocyte development
Cellular component: extracellular exosome; hemoglobin complex; nucleoplasm; haptoglobin-hemoglobin complex
Genetic constraint (gnomAD): Loss-of-function variants: 2 observed, 2.52 expected, observed/expected ratio (o/e) 0.8, 90% interval 0.31 to 1.82. That is too few expected variants to judge how well the gene tolerates losing a copy. Missense variants: 33 observed, 39.9 expected, observed/expected ratio (o/e) 0.83, 90% interval 0.63 to 1.11. Synonymous variants: 21 observed, 18.36 expected, observed/expected ratio (o/e) 1.14, 90% interval 0.81 to 1.64.
Homologues: Orthologues: chimpanzee HBZ (99% identical), pig HBZ (84% identical), guinea pig HBZ (82% identical), rat Hbz (80% identical), mouse Hba-x (78% identical), tropical clawed frog hba4 (65% identical), tropical clawed frog hba3 (61% identical), tropical clawed frog hbz (61% identical), Drosophila melanogaster glob1 (24% identical), Caenorhabditis elegans glb-14 (19% identical), Caenorhabditis elegans glb-34 (19% identical). Paralogues in human: HBA1 (60% identical), HBA2 (60% identical), HBQ1 (52% identical), HBM (47% identical), HBG1 (40% identical), HBG2 (40% identical), HBE1 (39% identical), HBD (39% identical), HBB (37% identical), CYGB (34% identical), MB (27% identical).
Diseases named in the same sentence as HBZ in open-access papers:
HBZ is named in the same sentence as 20 diseases in open-access papers, as found by Europe PMC text mining. Sharing a sentence is not in itself a finding about the gene and the disease. The quoted sentences say what the papers report.
adult T-cell leukemia/lymphoma (4 papers, 2021 to 2023). A peripheral (mature) T-cell neoplasm linked to the human T-cell leukemia virus type 1 (HTLV-1), adult T-cell leukemia/lymphoma is endemic in several regions of the world, in particular Japan, the Caribbean, and parts of Central Africa. "HTLV-1 is associated with adult T-cell leukemia/lymphoma (ATLL) and specifically encodes the TF HBZ." (PMID 36720920, 2023). "Furthermore, HBZ is the only HTLV-1-encoded TF that is expressed in all adult T-cell leukemia/lymphoma (ATLL) cases." (PMID 37501079, 2023). "Among Tax- and HBZ-dependent splicing changes, we identify events that are also altered in Adult T cell leukemia/lymphoma (ATLL) samples from two independent patient cohorts, and in well-known cancer census genes." (PMID 34543356, 2021).
leukemia (3 papers, 2014 to 2025). A malignant (clonal) hematologic disorder, involving hematopoietic stem cells and characterized by the presence of primitive or atypical myeloid or lymphoid cells in the bone marrow and the blood. "Transgenic mice for HTLV-1 Tax and HBZ are useful tools for understanding the role of these genes in the pathogenesis of HTLV-1-related leukemia and lymphoma (ATL)." (PMID 37511495, 2023). "In the majority of cases of leukemia caused by HTLV-1, only a single viral gene, hbz, and its cognate protein, HBZ, are expressed and their importance is increasingly being recognized in the development of HTLV-1-associated disease." (PMID 25389759, 2014).
viral infection (3 papers, 2014 to 2023). "Understanding how Rex, Tax, and HBZ expression is altered by cell signaling and cellular physiology to affect latency establishment and viral reactivation can facilitate the control of viral infection to prevent progression to disease." (PMID 24699669, 2014). "In viral infections, UBR5 could target and degrade human T cell leukemia virus type 1 (HTLV-1) antisense-derived protein (HBZ) to maintain the proliferative phenotype of transformed T-cell lines." (PMID 35980206, 2022).
colorectal cancer (2 papers, 2021 to 2022). A primary or metastatic malignant neoplasm that affects the colon or rectum. "Different types of Hbs (including HBE1 and HBZ) have been detected in glioblastoma cell lines, while HBE1 has been associated with radio-resistance in colorectal cancer cells." (PMID 36519745, 2022).
T-cell lymphoma (2 papers, 2020 to 2021). "Although some studies imply that HBZ is not essential for HTLV-1-induced immortalization, HBZ has been shown to positively affect T-cell proliferation, and that transgenic mice expressing HBZ developed T-cell lymphoma." (PMID 34835027, 2021). "In this study, HBZ expression resulted in the proliferation of HTLV-1-infected T-cell lymphoma and ATL cell lines, highlighting the importance of HBZ as a viral oncogene." (PMID 32674309, 2020).
anemia (1 paper, 2022). A reduction in the number of red blood cells, the amount of hemoglobin, and/or the volume of packed red blood cells. "In addition, the potentially related diseases to specific patients’ proteins were anemias or hematopoietic system diseases (proteins HBZ, EPB41, HP, PGK1, HBE1, BPGM, and ALDOA)." (PMID 36519745, 2022).
Hypercalcemia (1 paper, 2017). An abnormally increased calcium concentration in the blood. "In Gzmb-HBZ transgenic mice, development of bone loss and hypercalcemia coincided with lymphoproliferative disease, demonstrating HBZ-mediated bone loss in vivo for the first time." (PMID 29050201, 2017). "We found that in addition to Granzyme B and HBZ, PTHrP was significantly increased in T cells isolated from Gzmb-HBZ mice, providing the first in vivo evidence that HBZ could mediate hypercalcemia through enhanced PTHrP expression." (PMID 29050201, 2017).
latent infection (1 paper, 2014). "We show that HTLV-1 infection in culture can lead to two alternative outcomes — productive infection accompanied by senescence or latent infection followed by clonal expansion — based on the relative expression of regulatory proteins: Tax, Rex, and HBZ." (PMID 24699669, 2014). "When Tax/Rex expression is muted and HBZ is dominant, latent infection is established with expression of regulatory (Tax/Rex/HBZ) but not structural proteins." (PMID 24699669, 2014).
metastatic tumors (1 paper, 2017). "We thus demonstrated for the first time in an animal model, that the HTLV-1 oncogene HBZ might have an important role in ATL-mediated bone loss independent of Tax and suggest that HBZ-mediated bone loss may respond to current therapies for bone resident and metastatic tumors." (PMID 29050201, 2017).
tumor (10 papers, 2011 to 2026). "We recently reported that the viral protein, HBZ, activates expression of myoferlin (MyoF), which is overexpressed in several epithelial cancers where it promotes tumor cell metastasis." (PMID 42012183, 2026). "HTLV-1 Tax and HBZ transgenic mice spontaneously develop tumors, and the roles of both Tax and HBZ in cell transformation and tumor growth have been established." (PMID 37511495, 2023). "Once tumor formation occurs, Tax protein expression is repressed while HBZ continues to be ubiquitously expressed in ATL cells and HTLV-1 cells." (PMID 36146843, 2022). "Other examples from this study include well-described tumor-promoting genes such as SRSF2, DNMT3A, ATM, BRCA1 and PKM, for which Tax- and HBZ-alternative splicing events are now associated with ATLL for the first time." (PMID 34543356, 2021). "The continuous proliferation of ATL cells is likely driven by the chronically expressed viral oncoprotein, HBZ, acting as a tumor promoter." (PMID 32453758, 2020). "In addition, this tumor model is based on the overexpression of Tax and HBZ, which is different from actual tumorigenesis of HTLV-1-infected cells." (PMID 37511495, 2023). "HBZ promotes the expression of hot genes telomerase reverse transcriptase (hTERT) and JunD, which mitigates the effect of repeated mitosis on cellular senescence, thus promoting the survival of the tumor." (PMID 36146843, 2022). "Interestingly, independent expression of HTLV-1 oncogenes Tax and HBZ by the same promoter, Granzyme B, resulted in very different tumor phenotypes in transgenic mice." (PMID 29050201, 2017). "Another possibility is that low HBZ expression in the tumor could indicate that HBZ is indirectly effecting tumor formation through inflammation or other signaling pathways." (PMID 29050201, 2017). "Transgenic mouse models have greatly contributed to the analysis of Tax and HBZ in the transformation of HTLV-1-infected cells and tumor growth." (PMID 37511495, 2023). "HBZ, HTLV-1 basic leucine zipper transcription factor, promotes tumor cell proliferation and disrupts Wnt pathway modulators; however, its role in ATL induced osteolytic bone loss is unknown." (PMID 29050201, 2017). "Deletion of HBZ expression, however, from infectious molecular clones of HTLV-1 resulted in decreased in proviral load and antibody responses in the rabbit model and knock down of HBZ expression reduces tumor growth in a mouse model of ATL." (PMID 21994774, 2011). "Several studies have shown little, if any, viral structural, enzymatic, or regulatory gene expression in ATL, with the exception of the antisense gene HBZ,5,64,65 and it remains controversial whether the continued expression of non-HBZ viral genes is required for tumor maintenance." (PMID 30657736, 2019).
infection (8 papers, 2011 to 2025). The state of being infected such as from the introduction of a foreign agent such as serum, vaccine, antigenic substance or organism. "Another possible question is about the role of TAX and HBZ in changing hosts susceptible to infection?" (PMID 35911645, 2022). "The point around TAX and HBZ protein application for specific therapeutic antibody production is that these viral elements are expressed in a pathogenic state of infection." (PMID 35911645, 2022). "In the current study, we provide evidence that HBZ induces expression of MyoF, which also contributes to infection." (PMID 36827461, 2023). "The dynamically evolving proviral integration patterns in asymptomatic HTLV-1 carriers can now be explained by viral reactivation and de novo infection of naïve cells brought about via up-regulation of Rex and/or down-regulation of HBZ expression." (PMID 24699669, 2014). "We believe that targeting the interaction between p300/CBP and HBZ would be an effective strategy to prevent the deregulated expression of these genes, thereby reducing the intercellular spread of HTLV-1 and pathogenic effects associated with infection." (PMID 36827461, 2023). "Finally, it should be pointed out that although existing HBZ antibody can detect HBZ after DNA transfection, its sensitivity is insufficient for detecting HBZ during infection." (PMID 24699669, 2014). "Thus, the balance between Tax and HBZ expression, determined by the sites of proviral integration and the availability of cellular transcription factors, can modulate the extent of viral replication and NF-κB activation during infection." (PMID 21552325, 2011). "Finally, there is no direct evidence of the mechanism of action and whether the shift of the cytokine expression profile is secondary to the downregulation of HTLV-I proteins (Tax and/or HBZ), inhibition of de-novo infection of T cells by HTLV-I, or an HTLV-I independent mechanism." (PMID 23962110, 2013). "To gain a clearer insight into how HBZ enhances HTLV-1 infection, we cross-referenced genes that are activated by HBZ and express proteins with functions that might relate to the infection process." (PMID 36827461, 2023).
cancer (3 papers, 2021 to 2024). A tumor composed of atypical neoplastic, often pleomorphic cells that invade other tissues. "As shown here, the retroviral proteins Tax and HBZ are excellent tools to analyze transcriptional dynamics in cancer cells, beyond the evaluation of mutated genes." (PMID 34543356, 2021). "One of the open questions is whether there is a direct connection between HBZ and cell energy deregulation, as the only missing cancer hallmark associated with HBZ." (PMID 35252867, 2022). "Direct HBZ connection with all essential cancer characteristics in vivo is yet to be confirmed to show a specific HBZ role in oncogenesis and to prove HBZ as an effective target for the development of new anti-HTLV-1 therapies." (PMID 35252867, 2022). "Our rationale is that exploring more broadly the similarities and differences of Tax and HBZ interactomes with TFs and RBPs would provide global and specific insights on how viral oncogenes cooperate in the initiation and maintenance of cancer." (PMID 34543356, 2021). "A significant overlap was also found between genes corresponding to Tax or HBZ splicing pre-mRNA targets and known cancer census genes (ncg.kcl.ac.uk and cancer.sanger.ac.uk) (P = 0.02247 for Tax and P = 0.001742 for HBZ)." (PMID 34543356, 2021). "Pre-mRNA of 33 and 63 cancer genes were identified as splicing targets of Tax and HBZ, respectively." (PMID 34543356, 2021). "Interestingly, Tax- and HBZ-dependent splicing events also affected 33 and 63 genes that are also included in the Catalogue of Somatic Mutations in Cancer (COSMIC), as part of the cancer gene census." (PMID 34543356, 2021). "While HBZ appears to specifically target the IL-6-JAK-STAT3 pathway, cancer-related gene products of the PI3K-AKT-mTOR, TGF-β and IL-2-STAT5 pathways are more enriched in the Tax interactome." (PMID 34543356, 2021). "We identified genes for which ASEs were observed in both the Afro-Caribbean cohort and the Jurkat cells expressing Tax or HBZ, including cancer genes EIF4A2, IKBKB, LZTR1, STAT6 (for Tax); CARS, MDM2, IKZF1 (for HBZ); and EWSR1, MUTYH, and PTPRC (for both Tax and HBZ)." (PMID 34543356, 2021).
HBZ also shares sentences with these, for which no sentence is quoted: lymphoma (3 papers); Myelopathy (2); abortion (1); bronchiectasis (1); glioblastoma (1); hematopoietic system diseases (1); malaria (1); T-cell leukemia (1).